MUC5B (mucin 5B, oligomeric mucus/gel-forming)
Diseases named in the same sentence as MUC5B in open-access papers (continued):
Sharing a sentence is not in itself a finding about the gene and the disease.
asthma (continued). "We found that MUC5AC concentration was increased in children with asthma compared with that in control subjects, particularly in children with acute asthma, resulting in a significant change in the MUC5B:MUC5AC ratio." (PMID 28716644, 2017). "We quantified the principal airway mucins MUC5AC and MUC5B in the sputum of age-matched children with acute and stable asthma and healthy control subjects by using Western blotting." (PMID 28716644, 2017). "In contrast, two-thirds of samples from patients with stable asthma consisted of the high-charge glycoform of MUC5B alone." (PMID 28716644, 2017). "MUC5AC and MUC5B gene expression is altered in asthma, and recent work sheds light on their contribution to asthma pathogenesis." (PMID 29186064, 2017). "In control subjects and children with stable asthma, the geometric means of the MUC5B:MUC5AC ratios were 31.6 and 9.33, respectively (P = .119), and the mean difference was 3.37 (95% CI, 0.71-15.92)." (PMID 28716644, 2017). "Concentrations of MUC5B were similar in all three groups, with geometric means of 238.5, 208.4 and 165.9 μg/mL for the control subject, stable asthma, and acute asthma groups, respectively." (PMID 28716644, 2017). "Individuals with type 2 high asthma also have elevated levels of MUC5AC compared with healthy controls or individuals with type 2 low asthma; a substantial decrease in MUC5B expression is also observed in type 2 high asthma." (PMID 29186064, 2017). "In contrast, the high-charge MUC5B glycoform alone was present in approximately two-thirds (67%) of children with stable asthma, with the remaining 33% consisting of both high- and low-charge glycoforms." (PMID 28716644, 2017). "The loss of ER stress protein anterior gradient homolog 2 reduced overproduction of MUC5AC and MUC5B in individuals with asthma and in mouse models of allergic airway disease." (PMID 26599511, 2015). "The ER protein anterior gradient homolog 2 increases with overproduction of the mucins of 5AC (MUC5AC) and MUC5B in individuals with asthma and in mouse models of allergic airway disease." (PMID 26599511, 2015). "Among the secreted mucins, MUC5B secretion is abnormally augmented in many airway diseases, such as chronic bronchitis, chronic obstructive pulmonary disease, asthma and cystic fibrosis." (PMID 25733373, 2015). "Furthermore, these inflammatory ecosystems were found to contain a variety of components dysregulated during asthma, such as mucous production (that is, MUC5B)." (PMID 40399607, 2025). "Furthermore, Western blot analysis of lung tissues revealed that EPO-BM-MSCs markedly suppressed the expression of mucin markers MUC5AC and MUC5B in OVA-induced asthma mice." (PMID 41023810, 2025). "Therefore, regulating MUC5B expression is as important as regulating MUC5AC for effective asthma treatment." (PMID 40869396, 2025). "Additionally, the induction of MUC5AC and MUC2 and the repression of MUC5B were seen, which are specific to Th2-high asthma." (PMID 41303221, 2025). "In contrast, the level of ST3GAL3-catalyzed sialylation of MUC5B is downregulated in most patients with asthma, and a reduced MUC5B level may be related to the severity of the disease." (PMID 37256139, 2023). "Two mucins, MUC5AC and MUC5B, were reported to be the most involved in asthma pathogenesis." (PMID 38259471, 2023). "Altered or lower MUC5B gene expression correlates with and contributes to asthma pathogenesis." (PMID 37241840, 2023). "There was also a nonsignificant trend for MUC5B to have a reduced mRNA level in the presence of the moderate-to-severe asthma risk allele." (PMID 37263751, 2023). "In other disease settings, MUC5AC mRNA is increased in asthma, whereas MUC5B levels are decreased." (PMID 37005656, 2023). "Moreover, the clustergram results showed there was an overlap of gene expression between the input asthma-related genes and the genes perturbated by lovastatin and indicated that MUC5B was an overlapping hub gene." (PMID 37241840, 2023).
asthma (continued). "Neutrophil inflammation stimulated T1 or T17 cell release in T2-low asthma and induced Muc5ac and Muc5b expression in bronchial epithelial cells, which led to goblet cell proliferation, airway remodeling, glucocorticoid resistance, and the occurrence and development of severe or refractory asthma." (PMID 35685599, 2022). "This altered ratio of MUC5AC to MUC5B in asthma might be partially explained by the opposite effect of our novel asthma risk allele (G) of rs11603634 on MUC5AC and MUC5B production." (PMID 30552067, 2019). "However, in recent years, MUC5B has been shown to have physiologic functions in the mucus that ensure its normal clearance, and the levels of MUC5B in asthma remain stable or even decrease in some cases." (PMID 31692453, 2019). "Variants in the 11p15 MUC5B and MUC5AC locus have been associated with AHR in asthma." (PMID 29186064, 2017). "Increased MUC5AC and MUC5B protein have been reported in sputum from individuals with asthma." (PMID 29186064, 2017). "We also demonstrated that MUC5AC and MUC5B form distinct extracellular domains and that IL-13 induces a heterogeneous gel, which could have implications for mucociliary clearance in asthma." (PMID 29186064, 2017). "The contribution of glandular MUC5B to mucus dysfunction in asthma requires further exploration." (PMID 29186064, 2017). "Many individuals with asthma have increased MUC5AC mRNA levels but decreased MUC5B mRNA levels." (PMID 29186064, 2017). "Our data suggests that site-specific longitudinal intra-individual DNA methylation changes in MUC5B may play a role in the pathogenesis and development of asthma." (PMID 26691723, 2015). "Given that previous studies have identified eQTL for MUC5AC in asthma and MUC5B in IPF located near the genes themselves (“local eQTL”), one potential a priori prediction could have been that these same variants would be associated with MUC5AC and MUC5B protein concentrations." (PMID 37352370, 2023). "Moreover, L1000CDS2 clustergram analysis of the gene expression signatures showed that lovastatin, an approved drug for lipid lowering, may perturb MUC5B expression and have the potential for treating adult asthma." (PMID 37241840, 2023). "Above all, lovastatin may have beneficial pharmacological effects in asthma via hub target MUC5B." (PMID 37241840, 2023). "Accordingly, knowledge of MUC5B structure and its interactions with itself and other proteins is critical to better understand airway mucus biology and improve the management of lung diseases such as asthma, cystic fibrosis, and chronic obstructive pulmonary disease (COPD)." (PMID 31570524, 2019). "Therefore, examining expression of muc5AC and muc5B in the sputum of people with asthma provided tachykinin receptor antagonists might be especially important." (PMID 30081920, 2018). "Although we were not able to find any studies concerning the effects of VIP on muc5B regulation and/or expression in asthma, since muc5B might be decreased in asthma, and VIP might also be decreased, then one speculation is that VIP directly stimulates production of muc5B." (PMID 30081920, 2018). "However, changes in the relative proportion of MUC5AC and MUC5B are observed in asthma." (PMID 29186064, 2017). "We found that mucus plugs from patients with asthma were rich in MUC5AC, whereas those from patients with COPD were rich in MUC5B, and the ratio of MUC5AC to MUC5B was significantly higher in asthma than in COPD." (PMID 40091838, 2025). "By comparing the enriched signaling pathways in mild asthma and healthy controls, we identified “IL-17 signaling pathway” as the only important signaling pathway in which MUC5AC, MUC5B and CXCL8 showed significant enrichment." (PMID 38351296, 2024). "These mucous cells produce the mucin glycoprotein (MUC), the predominant form in the airways being MUC5AC; and the submucosal glands mainly produce MUC5B, with MUC5B being predominant under normal conditions and MUC5AC over-regulated in asthma." (PMID 37841931, 2023).
asthma (continued). "MUC5B is generally considered to be the homeostatic mucin, whereas MUC5AC is more inflammatory, being strongly induced by T2 inflammation as well as other asthma-related environmental challenges, including particulate matter and cigarette smoke." (PMID 35347136, 2022). "In contrast to type 2 high asthma, the ratio of MUC5AC to MUC5B protein observed in our study was approximately 0.8 to 1.0." (PMID 35239513, 2022). "A recent study found 5 hub genes (SERPINB2, SERPINB4, LTF, MUC5B, and CST4) related to the pathogenesis of asthma in bronchial and nasal cells." (PMID 36076228, 2022). "The ratio between MUC5B and MUC5AC changes dramatically in asthma because MUC5AC expression and protein production are substantially upregulated in asthmatic patients." (PMID 32411147, 2020). "To date, more than 20 human mucin genes have been identified, and the principal airway gel-forming mucins in asthma are MUC5AC and MUC5B." (PMID 31692453, 2019). "In our study, MUC5AC and MUC5B mRNA levels were significantly increased in asthma mice compared to those in control mice, and Baicalein treatment induced substantial decreases in MUC5AC and MUC5B mRNA expression levels." (PMID 31692453, 2019). "In asthma, MUC5AC levels are significantly increased, whereas MUC5B levels remain stable or decrease, compared with healthy lungs." (PMID 30154090, 2018). "We found a similar relationship between eosinophils and concentrations of MUC5B and MUC5AC in stable asthma." (PMID 28716644, 2017). "The proportion of sputum eosinophils was significantly greater in children with asthma than in control subjects, and we found that total mucin, MUC5AC, and MUC5B were correlated with sputum eosinophils in children with stable disease." (PMID 28716644, 2017). "In asthma as in health, MUC5AC is produced in goblet cells from the surface epithelium, while MUC5B is largely produced in the submucosal glands." (PMID 29186064, 2017). "In human, it has been reported that MUC5AC expression, measured using real-time RT-PCR, is much higher than both MUC5B and MUC4 in homogenates of endobronchial biopsies from healthy subjects or subjects with asthma." (PMID 17550583, 2007). "Our results suggest that liquiritin may help mitigate asthma symptoms by inhibiting both intracellular and secreted levels of MUC5AC and MUC5B through suppression of ERK and p38 signaling." (PMID 40869396, 2025). "Asthma granulocytic mucus plugs are therefore characterized by high number of granulocytes that release extracellular traps and by a mucin profile that includes both MUC5AC and MUC5B mucins." (PMID 40091838, 2025). "Given that the role of MUC5B in the pathogenesis of asthma has been extensively studied, this particular gene was not addressed in the present study." (PMID 39176391, 2024). "Since sialic acid contributes to the overall charge of MUC5B, we hypothesized that reducing sialylation would result in a lower charged mucin, similar to the predominate forms in COPD and asthma." (PMID 38853971, 2024). "Sputum plugs from people with severe asthma have previously been shown to contain more MUC5AC than MUC5B, which may have contributed to the increased detection of MUC5AC versus MUC5B in our studies." (PMID 35239513, 2022). "While an increased expression of Muc5b, another major mucin produced from airway submucosal glands, was noted in the airways of asthma mouse model, no clear dose-dependent response was observed in the cockroach allergen-treated HBECs." (PMID 34868022, 2021). "In our study, we examined the expression levels of critical members of the mucin family, specifically the secreted mucins MUC5AC and MUC5B, in addition to the membrane-bound mucins (MUC1, MUC4, and MUC2) in lung tissue obtained from the TIMPKO murine asthma model." (PMID 34221020, 2021). "In vivo, daily treatment with budesonide did not modify MUC5AC and MUC5B expression in bronchial biopsies from patients with mild asthma." (PMID 34248677, 2021).
asthma (continued). "MUC5B was in the top 10 genes most negatively related to a blood eosinophil count in both asthma and COPD, but did not meet FDR criteria in the COPD group." (PMID 31506971, 2020). "There are currently no studies available that provide information regarding the role of NKB in regulating muc5AC or muc5B expression, nor of SubP or NKA in the regulation of muc5B, in asthma." (PMID 30081920, 2018). "Several studies have compared the size distribution of MUC5AC and MUC5B in sputum from patients with asthma, yet no discernible difference has been observed." (PMID 29186064, 2017). "Interestingly, within the asthma cohort, a higher ratio of MUC5AC to MUC5B correlated with type 2 inflammation (>2% eosinophils)." (PMID 29186064, 2017). "Jinnai et al9 reported an association between airway eosinophils and total mucin concentration in the sputum of adults with stable asthma; they did not distinguish between MUC5B or MUC5AC." (PMID 28716644, 2017). "In murine asthma models, Muc5ac deletion reduces allergen-induced mucus plugging and airway hyperresponsiveness, indicating that MUC5AC is required for these pathological features, whereas Muc5b deficiency does not confer comparable protection." (PMID 41561092, 2025). "Although the number of goblet cells expressing MUC5B was similar in asthma airways with mucus plugs, unplugged asthma airways, and lung disease–free control airways, the number of goblet cells expressing MUC5AC was significantly higher in asthma airways occluded with mucus plugs." (PMID 40091838, 2025). "The granulocytic plugs in nonfatal asthma were characterized by a balanced mixture of MUC5AC and MUC5B mucins and the presence of extracellular DNA traps." (PMID 40091838, 2025). "MUC5B, ORMDL3, MUC5AC, CHI3L1, CLCA1, and IL-33 displayed a high non-specific relationship with allergic and nonallergic asthma." (PMID 33936056, 2021). "Thus, Muc5ac, but not Muc5b, may be a major airway mucin selectively responding to cockroach allergen, highlighting that study targeting Muc5ac may have therapeutic potential in unplugging the airway mucus in asthma." (PMID 34868022, 2021).
COVID-19 (35 papers, 2020 to 2025). A disease caused by infection with severe acute respiratory syndrome coronavirus 2. "Though increased mucus plugging was observed in COVID-19 lung autopsies, the same allele associated with increased MUC5B is protective against severe COVID-19, suggesting increased mucus production in this acute context is protective." (PMID 39876559, 2025). "When using sentinels PRSs calculated from the previously known IPF risk variants, the association with COVID-19 hospitalisation was only significant for models where the MUC5B locus had been excluded." (PMID 40247961, 2025). "Although the exact biological mechanisms remain to be fully elucidated, the observed association between MUC5B polymorphisms and decreased COVID-19 severity underscores the gene’s potential role in respiratory defense." (PMID 40543387, 2025). "The rs35705950-T polymorphism in MUC5B, a gain-of-function variant, has been investigated for its impact on COVID-19 severity." (PMID 40543387, 2025). "In the autopsied lungs of COVID-19 patients, the mucus accumulation is caused by Muc5b overexpression, induced by SARS-CoV-2." (PMID 38999930, 2024). "Other researchers also showed that SARS-CoV-2 infection is associated with a high prevalence of MUC5B-dominated mucus plugging in the distal lung, and MUC5B expression was increased in airway regions of COVID-19 autopsy lungs." (PMID 38392851, 2024). "The MUC5B genetic variant rs35705950 is associated with higher expression of the soluble mucin MUC5B and underrepresented in COVID-19 patients compared to healthy individuals, suggesting a protective role for MUC5B." (PMID 37561789, 2023). "In a separate study of MVP participants tested for COVID-19, we identified a significant mediating effect of the MUC5B variant in reducing risk for pneumonia due to COVID-19." (PMID 35482673, 2022). "We observed a significant association between the MUC5B rs35705950 promoter polymorphism and severe COVID-19 in four white European cohorts." (PMID 34888316, 2021). "Meta-analyses were performed to analyze the association of MUC5B rs35705950 with severe COVID-19, both for comparison of allele contrast and for a dominant T-allele carriage model (GT+TT vs. GG)." (PMID 34888316, 2021). "The results of the meta-analyses demonstrate the protective effect of the MUC5B T allele against severe COVID-19." (PMID 34888316, 2021). "In a separate study of MVP participants tested for COVID-19, we identified a significant mediating effect of the MUC5B variant in reducing risk for pneumonia due to COVID-1925." (PMID 34642702, 2021). "In conclusion, we found that carriage of the T-allele of MUC5B rs35705950 confers protection from development of severe COVID-19." (PMID 34888316, 2021). "They found that genetically increased risk of IPF indeed associated with increased COVID-19 severity, except for the MUC5B allele." (PMID 34888316, 2021). "COVID-19 patients also have a lower allelic frequency of the MUC5B genetic variant rs35705950 than healthy controls, which is associated with a higher level of expression of MUC5B, suggesting a protective role for MUC5B." (PMID 33184103, 2020). "Further research is warranted to validate these hypotheses and to assess the viability of MUC5B as a candidate gene for therapeutic targeting and risk stratification in COVID-19." (PMID 40543387, 2025). "Moreover, respiratory mucus accumulation has been associated with Muc5b overexpression in the autopsied lungs of COVID-19 patients." (PMID 38999930, 2024). "In this study we used a candidate gene case-control approach to examine whether a genetic polymorphism that influences expression of MUC5B is associated with susceptibility to severe COVID-19." (PMID 34888316, 2021). "We investigated if MUC5B rs35705950 associates with severe COVID-19." (PMID 34888316, 2021). "However, further studies are needed to investigate if the MUC5B polymorphism will associate with specific COVID-19 severity scores." (PMID 34888316, 2021).